KCNU1 (potassium calcium-activated channel subfamily U member 1)
Description:
Testis-specific potassium channel activated by both intracellular pH and membrane voltage that mediates export of K(+). Represents the primary spermatozoan K(+) current. The channel underlies a pH-triggered membrane hyperpolarization during the process of sperm capacitation, as sperm encounter the alkaline environment near the ovum in the female reproductive tract, thereby playing an essential for male fertility.
Synonyms: KCNMA3; KCNMC1; SLO3; KCa5.1; KCa5; SPGF79
Tractability: Small molecule: it belongs to a druggable protein family. Antibody: its Gene Ontology location is reachable by antibodies, with high confidence; UniProt places it where antibodies can reach, with medium confidence; UniProt predicts a signal peptide or a membrane-spanning region; the Human Protein Atlas places it where antibodies can reach.
Gene: Protein-coding gene on chromosome 8 (36,784,324 to 36,936,125, forward strand). Ensembl gene ENSG00000215262.
Subcellular location: Cell membrane; Cell projection, cilium, flagellum membrane
Subcellular location (Human Protein Atlas): Plasma membrane; Principal piece
Pathways (Reactome):
Reproduction: Sperm Motility And Taxes
Gene Ontology:
Molecular function: potassium channel activity; large conductance calcium-activated potassium channel activity; monoatomic ion channel activity
Biological process: potassium ion transmembrane transport; reproductive process; monoatomic ion transport; potassium ion transport; transmembrane transport
Cellular component: sperm flagellum; membrane; plasma membrane
Genetic constraint (gnomAD): Loss-of-function variants: 40 observed, 50.37 expected, observed/expected ratio (o/e) 0.79, 90% interval 0.62 to 1.03. The upper end of that interval is the gene's LOEUF score, 1.03, which puts it in group 4 of 6, group 1 being the genes least tolerant of losing a copy. Missense variants: 697 observed, 751.13 expected, observed/expected ratio (o/e) 0.93, 90% interval 0.87 to 0.99. Synonymous variants: 284 observed, 291.65 expected, observed/expected ratio (o/e) 0.97, 90% interval 0.88 to 1.07.
Homologues: Orthologues: chimpanzee KCNU1 (99% identical), macaque KCNU1 (92% identical), dog KCNU1 (73% identical), pig KCNU1 (67% identical), rat Kcnu1 (64% identical), mouse Kcnu1 (63% identical), guinea pig KCNU1 (63% identical), Drosophila melanogaster SLO2 (18% identical), Caenorhabditis elegans slo-2 (15% identical). Paralogues in human: KCNMA1 (42% identical), KCNT1 (19% identical), KCNT2 (18% identical).
Diseases named in the same sentence as KCNU1 in open-access papers:
KCNU1 is named in the same sentence as 9 diseases in open-access papers, as found by Europe PMC text mining. Sharing a sentence is not in itself a finding about the gene and the disease. The quoted sentences say what the papers report.
Infertility (11 papers, 2014 to 2025). "In mice, the SLO3 channel is responsible for KSper, and deletion of Kcnu1, the gene that encode SLO3, inhibited the alkalinization-induced K+ current, and caused infertility." (PMID 37108159, 2023). "Studies in mice have confirmed that the Slo3 subunit of the potassium channel (KCNU1) is essential for fertility, and any disturbance within the channel cause infertility in mice." (PMID 36101387, 2022). "In addition, the Potassium Channel, Subfamily U, Member-1 (KCNU1), mediates sperm membrane hyperpolarization and acrosome exocytosis, and men from consanguineous families and mice lacking KCNU1 are infertile due to impaired acrosome exocytosis and zona penetration." (PMID 38764035, 2024).
asthenozoospermia (2 papers, 2017 to 2023). "In our study, we detected an increase of SLO3/KCNU1 gene expression in the oligozoospermia and oligoasthenoteratozoospermia groups and a decrease in the asthenozoospermia group compared with the control." (PMID 29492471, 2017). "SLO3/KCNU1 gene expression decreased in the oligozoospermia, asthenozoospermia and teratozoospermia groups compared to the control but no significant change was observed in the oligoasthenoteratozoospermia group." (PMID 29492471, 2017). "In this study CatSper1, 2, 3, 4, KCNU1, Hv1, and TMEM16 ion channel expressions were studied in infertile men with oligoasthenospermia, isolated asthenozoospermia, teratozoospermia, and oligozoospermia in comparison with fertile individuals with normal sperm parameters." (PMID 29492471, 2017).
lung carcinoma (1 paper, 2025). "Lung cancer studies included E3 (KCNK1), E8 (KCNK1, KCNN4), E12 (KCNH8, KCNMB2), E23 (KCNU1), E30 (KCNQ5-IT1), E35 (KCNK1), E43 (KCNK6), E49 (KCNN4), 2), E54 (KCNJ13), E63 (KCNK12), and E67 (KCNMB2)." (PMID 40867621, 2025).
teratozoospermia (1 paper, 2017). "No significant change was observed in the teratozoospermia group regarding the SLO3/KCNU1 gene expression." (PMID 29492471, 2017).
cancer (1 paper, 2025). A tumor composed of atypical neoplastic, often pleomorphic cells that invade other tissues. "Among these were known cancer-testis antigens, previously reported TAAs, and novel candidates such as KCNU1 and OR10G2, which merit further functional validation." (PMID 41437377, 2025). "The remaining nine class I peptides were reference peptides, eight of which originated from six genes (MAGEA3, MAGEA6, BRDT, DAZ1, KCNU1, and IGF2BP1) that are expressed in testis but absent from oGTEx and mTECs, with some already known as cancer/testis (C/T) antigens." (PMID 41437377, 2025).
Cardiovascular disease (1 paper, 2024). "Among these, 10 regions, proximal to or within the genes OVAAL, BMP3, RIOK1, AC096553.5, MCPH1, KCNU1, GLIS3, TUT7, TRIB3, and SYNDIG1, represent novel associations with MI and have not been previously linked to Cardiovascular disease (CVD)-related traits." (PMID 38725839, 2024).
KCNU1 also shares sentences with these, for which no sentence is quoted: male infertility (1 paper); oligoasthenoteratozoospermia (1); tumours (1).